USP18 (ubiquitin specific peptidase 18)
Diseases named in the same sentence as USP18 in open-access papers (continued):
Sharing a sentence is not in itself a finding about the gene and the disease.
breast tumor (3 papers, 2018 to 2025). "USP-18 mRNA level was significantly higher in ER+- than in ER--breast tumor tissues and in their corresponding tumor-adjacent tissues." (PMID 29416786, 2018). "In human breast tumor tissues, SLC7A11 levels were negatively or positively correlated with KCTD10 or USP18, respectively." (PMID 38959043, 2024). "Given breast tumor growth was significantly suppressed in an in vivo xenograft model following neddylation blockage and SLC7A11 inhibition, it promoted us to determine whether targeting KCTD10 or USP18 in combination with SLC7A11 inhibition could similarly affect tumor growth in this model." (PMID 38959043, 2024).
Burkitt lymphoma (3 papers, 2009 to 2024). A rare form of malignant mature B-cell non-Hodgkin lymphoma. "In addition, a disorder in USP18 expression in Burkitt lymphoma can lead to interferon (IFN)-stimulated gene expression." (PMID 39664521, 2024). "In addition, dysregulation of USP18 expression leads to IFN-stimulated gene expression in Burkitt lymphoma." (PMID 34001679, 2021).
cervical cancer (3 papers, 2016 to 2022). A primary or metastatic malignant neoplasm involving the cervix. "The high expression of USP18 was found in cervical cancer cells which enhanced cell proliferation and hampered apoptosis via PI3K/Akt signaling pathway." (PMID 36582601, 2022). "Silencing USP18 in SiHa and Caski cervical cancer cell lines inhibited cell proliferation, induced apoptosis, and promoted cleaved caspase-3 expression." (PMID 32770981, 2020). "The present findings demonstrated that USP18 was overexpressed in cervical cancer specimens and cell lines." (PMID 32770981, 2020). "Second, our study not only elucidated the possible signalling pathway of USP18 in human cervical cancer cells but also provided evidence of its potential use as a target in cervical cancer treatment." (PMID 32770981, 2020). "Our results indicated that oeUSP18 rescued the function of USP18 in siUSP18-transfected cells, further demonstrating USP18’s role as an oncogene in human cervical cancer cells." (PMID 32770981, 2020). "Our analyses not only elucidated USP18’s role but also identified its potential signalling pathway in cervical cancer cells." (PMID 32770981, 2020). "We silenced and overexpressed USP18 in cervical cancer cells using RNA interference (RNAi) and lentiviral-mediated vector transfections, respectively." (PMID 32770981, 2020). "Quantitative real-time polymerase chain reaction (qRT-PCR) and immunohistochemical staining were performed to analyse USP18 levels in cervical cancer and matched to adjacent normal tissues." (PMID 32770981, 2020). "Next, we compared the relative mRNA and protein levels of USP18 between normal human cervical epithelial (HcerEpic) and cervical cancer cells, including Hela, C-33A, Caski, and SiHa." (PMID 32770981, 2020). "Correlation analysis indicated that USP18 was correlated with p-AKT expression in human cervical cancer tissues." (PMID 32770981, 2020). "First, our findings indicated that USP18 was increased in human cervical cancer tissues and promoted the progression of human cervical cancer cells." (PMID 32770981, 2020). "Together, these results suggested that USP18 silencing inhibited the tumorigenicity of human cervical cancer cells in vivo." (PMID 32770981, 2020). "However, USP18’s underlying function in human cervical cancer remains unclear." (PMID 32770981, 2020). "A Gene Set Enrichment Analysis revealed that USP18 was enriched in the PI3K/AKT signalling pathway in cervical cancer." (PMID 32770981, 2020). "Both the relative mRNA and protein levels of USP18 were upregulated significantly in cervical cancer cells (except for Hela), especially Caski and SiHa cells." (PMID 32770981, 2020). "In the current study, the downregulation of USP18 also significantly suppressed the proliferation of cervical cancer cells and induced cell apoptosis." (PMID 32770981, 2020). "In the current study, we aimed to analyse the role of USP18 and its signalling pathways in cervical cancer." (PMID 32770981, 2020). "Our findings not only deepened the understanding of USP18’s biological function in cervical cancer pathogenesis, but we also provided novel insight for cervical cancer therapy." (PMID 32770981, 2020). "In this study, USP18 knockdown significantly suppressed theAKT phosphorylation in cervical cancer cells." (PMID 32770981, 2020). "Our results also indicated that USP18 was overexpressed in human cervical cancer tissues." (PMID 32770981, 2020). "In vivo, USP18 silencing inhibited human cervical cancer cells’ tumorigenicity." (PMID 32770981, 2020). "Importantly, LY294002 significantly abolished the effects of USP18 overexpression in cervical cancer cells." (PMID 32770981, 2020). "The current study indicates that USP18 is an oncogenic gene in cervical cancer." (PMID 32770981, 2020). "The present study’s purpose was to explore USP18’s function in cervical cancer cells." (PMID 32770981, 2020). "In the present study, USP18 was suggested as an oncogene in human cervical cancer." (PMID 32770981, 2020).
cervical cancer (continued). "Our results suggest that USP18 might promote cell proliferation and inhibit the apoptosis of cervical cancer cells by regulating the PI3K/AKT pathway." (PMID 32770981, 2020). "In the present study, we explored USP18’s function in human cervical cancer cells." (PMID 32770981, 2020). "Additionally, 30 pairs of cervical cancer and matched adjacent para-cancer tissues were used to examine the mRNA level of USP18 further." (PMID 32770981, 2020). "Moreover, RNA interference (RNAi) and lentiviral-mediated vector transfections were performed to silence and overexpress USP18, respectively, in cervical cancer cells." (PMID 32770981, 2020). "Therefore, targeting USP18 provided novel insight into the treatment of cervical cancer." (PMID 32770981, 2020). "Hence, USP18 was involved in the regulation of the PI3K/AKT pathway in cervical cancer cells." (PMID 32770981, 2020). "Next, Western blot analysis was used to examine the protein levels of USP18 and phosphorylated AKT (p-AKT) in four pairs of human cervical cancer and matched adjacent para-cancer tissues." (PMID 32770981, 2020). "The PI3/AKT inhibitor LY294002 was used to block AKT’s endogenous activity to assess the relationship between USP18 and AKT in cervical cancer cells." (PMID 32770981, 2020). "Both USP18 and p-AKT were upregulated significantly in human cervical cancer tissues." (PMID 32770981, 2020). "Hence, the PI3K/AKT inhibitor LY294002 was used to determine the relationship between USP18 and AKT in cervical cancer cells." (PMID 32770981, 2020).
Dengue (3 papers, 2020 to 2024). "Our previous RNA-seq data showed a significant upregulation of USP18 in the dengue patients and are inversely correlated with the reduced levels of miR-191-5p that can target USP18." (PMID 32934118, 2020).
hepatitis C virus infection (3 papers, 2017 to 2025). A viral infection caused by the hepatitis C virus. "For example, silencing USP18 has been shown to promote the antiviral innate immunity against hepatitis C virus infection, while pharmacological inhibition of USP14 greatly suppresses murine norovirus infection." (PMID 40208866, 2025). "Since IFN-α and IFN-β are widely used to treat hepatitis B virus and hepatitis C virus infections, USP18 inhibitors may be an effective strategy for modulating IFN antiviral activity." (PMID 29285303, 2017).
Hydrocephalus (3 papers, 2007 to 2020). Hydrocephalus is an active distension of the ventricular system of the brain resulting from inadequate passage of CSF from its point of production within the cerebral ventricles to its point of absorption into the systemic circulation. "Additionally, USP18-deficient mice exhibited necrosis of ependymal cells concurrent with hydrocephalus and reduced life expectancy." (PMID 32957626, 2020).
Insulin resistance (3 papers, 2020 to 2023). Increased resistance towards insulin, that is, diminished effectiveness of insulin in reducing blood glucose levels. "USP18 is also downregulated in a mouse model of T2DM, and in transgenic mice, obesity-induced insulin resistance was ameliorated and aggravated by hepatocyte-selective Usp18 overexpression and deficiency, respectively." (PMID 36834633, 2023). "We then evaluated the level of insulin resistance in USP18-silenced cells by addressing AKT activation." (PMID 31971958, 2020). "From the transcriptomic analysis we selected USP18, previously shown to decrease inflammation and insulin-resistance." (PMID 31971958, 2020). "Interestingly, the level of inflammation and insulin resistance was increased in cells with reduced USP18 level." (PMID 31971958, 2020). "Therefore, DTG and ATV/r exerted opposite effects on the same three pathways, insulin resistance, senescence and inflammation, respectively independent and dependent on USP18." (PMID 31971958, 2020). "USP18 silencing increased basal insulin resistance (decreased AKT activation)." (PMID 31971958, 2020). "USP18 binds and deubiquitinates TAK1 to attenuate hepatic steatosis and insulin resistance in non-alcoholic liver disease." (PMID 37304282, 2023). "Accordingly, since TAK1 is required for JNK activation, leading to insulin resistance, and since USP18 inhibits TAK-1, an insulin-sensitizing effect of USP18 has been shown in the liver." (PMID 31971958, 2020).
leiomyosarcoma (3 papers, 2015 to 2017). An uncommon, aggressive malignant smooth muscle neoplasm, usually occurring in post-menopausal women. "In contrast, engineered loss of Usp18 led to development of leiomyosarcomas, but this is a strain specific effect." (PMID 27980214, 2017). "USP18 null mice and the derived cell lines represent clinically-relevant models of leiomyosarcoma and can provide insights into both leiomyosarcoma biology and therapy." (PMID 26555296, 2015). "USP18 analysis of clinical leiomyosarcoma revealed abundant staining in normal smooth muscle cells, which was retained by some sarcomas, but lost in others." (PMID 26555296, 2015). "Both murine USP18 null and human leiomyosarcoma cell lines described here responded independently to doxorubicin and type 1 IFN treatments." (PMID 26555296, 2015). "These murine sarcoma cell lines, when coupled with the parental USP18 null mice, comprise tractable models to accelerate the discovery and development of new therapies for human leiomyosarcoma." (PMID 26555296, 2015). "USP18 expression levels in clinical leiomyosarcoma varied widely with some staining at levels comparable to vascular smooth muscle and some with much lower levels." (PMID 26555296, 2015). "While loss of USP18 did not significantly impact overall survival or disease-free survival, it did significantly decrease the time to metastasis indicating a key role for USP18 levels in leiomyosarcoma clinical biology." (PMID 26555296, 2015). "USP18 null mice developed leiomyosarcomas with complex karyotypes and distinct genetic alterations reminiscent of human leiomyosarcomas." (PMID 26555296, 2015). "Immunohistochemical analyses of USP18 in human leiomyosarcomas revealed a range of staining intensities with the highest USP18 expression in normal vascular smooth muscle." (PMID 26555296, 2015). "USP18 tissue array analysis of primary leiomyosarcomas from 89 patients with a clinical database revealed cases with reduced USP18 levels had a significantly decreased time to metastasis (P = 0.0441)." (PMID 26555296, 2015). "USP18 null mice develop leiomyosarcoma recapitulating key features of clinical leiomyosarcomas and patients with reduced-USP18 tumor levels have an unfavorable outcome." (PMID 26555296, 2015). "Compared to normal tissues where USP18 staining was high, (vascular smooth muscle cells served as a control), there was a sub-group of leiomyosarcomas with reduced USP18 immunostaining." (PMID 26555296, 2015). "The IFN-hypersensitive environment found in USP18 null mice might deregulate proliferation of these vascular cells, initiating leiomyosarcoma formation." (PMID 26555296, 2015). "Findings revealed prominent USP18 immunostaining in lung macrophages and also in histopathologically normal vascular smooth muscle cells with reduced expression relative to the adjacent leiomyosarcoma." (PMID 26555296, 2015).
ovarian carcinoma (3 papers, 2021 to 2025). A malignant neoplasm originating from the surface ovarian epithelium. "The deubiquitination enzyme USP18 can also up-regulate ovarian cancer development in ovarian cancer by activating the AKT/mTOR signaling pathway through direct regulation of mTOR and AKT proteins." (PMID 39759114, 2025). "We also found increased ISG15 expression and an increased ISGylation profile in HGSOC patient tissues and in tumour and ascites derived from an orthotopic ovarian cancer mouse model along with USP18 and ISGylating enzyme TRIM25." (PMID 38939897, 2024).
atherosclerosis (2 papers, 2022 to 2025). A disease characterized by the build-up of fatty material and calcium deposition in the arterial wall resulting in partial or complete occlusion of the arterial lumen. "Thus, the evidence provided by our data underlines the protective influence of USP18 in atherosclerosis development." (PMID 39804798, 2025). "A different study has also indicated that ABCG1, degraded by UPS, potentially functions as a bridge in USP18‐regulated lipid metabolism during the development of atherosclerosis." (PMID 39804798, 2025). "Further, it suggests that USP18 knockdown encourages foam cell formation and expedites atherosclerosis progression by enhancing ABCG1 degradation." (PMID 39804798, 2025). "To conclude, our findings indicate the protective influence of USP18 on atherosclerosis as well as delineate its possible mechanism, suggesting that USP18 can potentially serve as a therapeutic target for atherosclerosis." (PMID 39804798, 2025). "This study endeavours to examine the impact of USP18 on atherosclerosis and elucidate its corresponding molecular mechanisms." (PMID 39804798, 2025). "In summarising our findings, we've presented evidence highlighting the beneficial role of USP18 in atherosclerosis." (PMID 39804798, 2025). "Taken collectively, these results suggest a correlation between USP18 and the progression of atherosclerosis." (PMID 39804798, 2025). "This study elucidates the pivotal role of USP18 in foam cell formation and atherosclerosis development." (PMID 39804798, 2025). "In summary, our results suggested that USP18 plays a crucial role in managing the progression of atherosclerosis by strengthening the expression of ABCG1 protein through its deubiquitinating effect on ABCG1." (PMID 39804798, 2025). "Although USP18 has been identified as significant in lipid metabolism regulation, its specific involvement in atherosclerosis remains ambiguous." (PMID 39804798, 2025). "This study thereby proposes that the progression of atherosclerosis may be modulated by USP18 through its regulation over ABCG1 expression." (PMID 39804798, 2025). "With this in view, our findings underscore the mechanism by which USP18 inhibits atherosclerosis development, signifying that USP18 targeting may serve as a potential strategy for atherosclerosis prevention and treatment." (PMID 39804798, 2025). "This study investigates the USP18 expression in dysregulated cholesterol metabolism diseases, like FH, through the GSE6054 dataset to project its potential role in atherosclerosis." (PMID 39804798, 2025). "Many atherosclerosis-related genes, such as ADAMTS2, ECM1, and USP18, showed changes in their expression." (PMID 35806463, 2022). "Firstly, we did not construct a distinctive macrophage knockout USP18 animal model, thereby restricting us from exploring the implications of macrophage‐specific USP18 on the evolution of atherosclerosis." (PMID 39804798, 2025).
Autoimmunity (2 papers, 2013 to 2024). The occurrence of an immune reaction against the organism's own cells or tissues. "In conclusion, Usp18-driven enforced viral replication in dendritic cells can break immunological tolerance and critically influences induction of autoimmunity." (PMID 24204252, 2013). "USP18 inhibits the NF-κB-signaling-mediated regulation of T-cell proliferation and IL-2 production by catalyzing the deubiquitination of the TGFβ-activated kinase/TAK-binding protein (TAB1/TAK1) complex, which provides evidence for USP18’s regulation of T-cell-mediated autoimmunity." (PMID 38675828, 2024).
chronic hepatitis B (2 papers, 2016 to 2020). "The expression level of USP18 was elevated in the pretreatment liver tissues of chronic hepatitis B(CHB) patients who did not respond to IFN treatment." (PMID 32248821, 2020). "Similarly, our clinical data revealed that chronic hepatitis B (CHB) patients who had pre-treated higher hepatic USP18 expression responded poorly (or called “non-response, NR”) to IFN treatment." (PMID 32248821, 2020).
chronic viral hepatitis (2 papers, 2019 to 2020). "USP18's role in viral hepatitis may reflect an underlying effect in the innate immune response." (PMID 31871427, 2019). "The ISG15/USP18 pathway is likely to play a role in viral hepatitis, again in a virus-specific manner." (PMID 31871427, 2019).
colitis (2 papers, 2017 to 2024). Inflammation of the colon. "Of note, Bst2, Socs1, and Usp18 showed significant induction in B. fragilis–monocolonized mice compared with GF mice during experimental colitis." (PMID 38085267, 2024). "After induction of acute colitis with DSS, we found with EdgeR and CuffDiff2 analyses that the expression of 11 genes (Clps, Ddx60, Fgb, Fgg, Ifi44, Ifit2, Isg15, Itih3, Itih4, Oas3 and Usp18), which are involved in antimicrobial response, was increased in MMP-9−/− compared to WT mice." (PMID 28561062, 2017).
diabetes (2 papers, 2013 to 2014). "Whether indeed the expression of interferon inhibitors such as Usp18 in certain cell types contributes to the risk of human diabetes remains to be tested." (PMID 24204252, 2013). "Blocking of virus replication by either depletion of dendritic cells, genetic depletion of Usp18 or pharmacological inhibition of replication blunted expansion of autoreactive CD8+ T cells and prevented diabetes." (PMID 24204252, 2013). "Therefore enhanced activity of Usp18 in beta islet cells would limit IFN-I signaling in these cells and could prevent diabetes during exposure to IFN-I." (PMID 24204252, 2013). "In conclusion, lack of Usp18 in CD11c+ cells reduced priming of islet-specific CD8+ T cells and prevented induction of diabetes." (PMID 24204252, 2013).
diffuse large B-cell lymphoma (2 papers, 2021 to 2024). "Therefore, it is likely that USP18 regulates IFN-I-associated immune responses to develop extranodal diffuse large B-cell lymphoma (EN DLBCL) with poor prognosis." (PMID 39664521, 2024).
esophageal squamous cell carcinoma (2 papers, 2023 to 2024). Esophageal squamous cell carcinoma (ESCC) is a type of esophageal carcinoma (EC) that can affect any part of the esophagus, but is usually located in the upper or middle third. "Another agent promoting EMT is ZEB1 deubiquitinated by ubiquitin-specific peptidase 18 (USP18) in esophageal squamous cell carcinoma, while overall SUMOylation is associated with cancer progression." (PMID 37174083, 2023). "Interestingly, USP18 expression has been shown to be upregulated in esophageal squamous cell carcinoma (ESCC) patients." (PMID 38675828, 2024).